INS (insulin)
Diseases named in the same sentence as INS in open-access papers (continued):
Sharing a sentence is not in itself a finding about the gene and the disease.
coronary artery disease (continued). "We have observed the effect of metformin use versus no-use on the risk of chronic urticaria among different groups of sex, coronary artery disease, chronic obstructive pulmonary disease, rheumatoid arthritis, psychosis, CCI, sulfonylureas, insulin, non-steroidal anti-inflammatory drugs, and statins." (PMID 36078769, 2022). "Intravascular ultrasound shows that insulin-treated patients with coronary artery disease have smaller external elastic membrane and lumen volumes than patients not treated with insulin, resulting in greater percent atheroma volume for a given total atheroma volume." (PMID 34158057, 2021). "Similarly, in the BARI-2D trial, in patients with ischemic heart disease, insulin provision was not superior to insulin sensitizers in the prevention of new events." (PMID 24348585, 2013). "However, this is in line with the findings of previous studies that have not demonstrated a clear relationship between insulin concentrations and the angiographically-assessed severity of coronary disease." (PMID 20509904, 2010). "There is a reduction in the levels of adiponectin in diabetics with coronary artery disease compared with diabetics without coronary artery disease and the adiponectin levels in serum are negatively correlated with basal metabolic rate, plasma glucose and insulin and serum triglycerides." (PMID 19644556, 2009).
Nephropathy (442 papers, 2006 to 2026). A nonspecific term referring to disease or damage of the kidneys. "Several studies have highlighted that OSA is independently associated with poorer glycemic control, increased insulin resistance, and an elevated risk of diabetic complications, including nephropathy, retinopathy, and neuropathy." (PMID 40565914, 2025). "Studies that measured eGDR and insulin sensitivity scores in persons with T1D also found reverse associations with retinopathy and its severity, and/or kidney disease." (PMID 39998445, 2025). "Elevated plasma FFA can lead to lipotoxicity, and lipotoxicity is associated with impaired pancreatic β-cell functioning, decreased systemic insulin sensitivity, and increased risk of cardiovascular and renal disorders." (PMID 39183283, 2024). "Increased miR-132 circulating levels have been associated with T2D and nephropathy and approaches to targeting it did impair blood glucose and improved insulin secretion." (PMID 35370692, 2022). "It is caused by a shortage of insulin or inadequate insulin synthesis in the pancreas, leading to severe complications such as diabetic neuropathy, nephropathy, retinopathy and cardiovascular disease." (PMID 35502486, 2022). "Nephropathy, another major microvascular complication, was linked to impaired glycemic control, increased body weight, and improper insulin dosage." (PMID 35721726, 2022). "Severe kidney disease was also predicted by many risk factors, but most clearly by insulin monotherapy, smoking and macroalbuminuria." (PMID 35821071, 2022). "Regarding those T2DM young patients at major risk of aggressive nephropathy, the study of a proper strategy to combine different hypoglycaemic drugs, alone or associated with insulin therapy, is of pivotal importance." (PMID 34577791, 2021). "The presence of nephropathy was associated with a higher TyG index (OR = 1.703, P < .001), greater age (OR = 1.031, P < .001), use of insulin (OR = 1.842, P = .033), higher systolic BP (OR = 1.015, P < .001), and the presence of DR (OR = 3.052, P < .001)." (PMID 33532603, 2021). "Other documented risk factors are renal disease/nephropathy, genetic factors, high waist-hip ratio (abdominal obesity), upper socioeconomic status, urban residence, male gender, insulin treatment and pregnancy." (PMID 32295571, 2020). "Intensive insulin therapy has proven to be the most effective treatment for preventing nephropathy progression in T1D; however, the underlying mechanisms remain incompletely understood." (PMID 31040360, 2019). "Intensive insulin therapy enables a profound reduction in microvascular complications (neuropathy, retinopathy, and nephropathy) commonly caused by T1D." (PMID 31013147, 2019). "It has been recognised for some time that kidney disease can cause loss of skeletal muscle insulin sensitivity." (PMID 31195596, 2019). "Intensive insulin therapy is critical for preventing the progression of nephropathy inT1D, although the underlying mechanisms remain incompletely understood." (PMID 28324005, 2017). "To better understand the beneficial effect of podocyte-specific insulin signaling deficiency for renal disease and the role of PHB2 on metabolic signaling in podocytes, we next generated a Phb2 knockdown podocyte cell culture model." (PMID 25643582, 2015). "However, insulin-treated patients generally have more severe and long-standing T2D, placing them at higher risk of kidney disease progression." (PMID 41011236, 2025). "ET has been shown to enhance insulin sensitivity, which mitigates kidney damage associated with DM." (PMID 39189216, 2024). "Other information lacking in some studies was the identification of diabetic complications (retinopathy, nephropathy, neuropathy), which could have affected the choice of insulin or fracture risk." (PMID 39054499, 2024).
Nephropathy (continued). "When compared with non-insulin treated patients, insulin treated ones showed less knowledge for identification of numbness and tingling (DKT-13), where the most frequent error was the association of kidney disease, particularly in the group of patients treated with insulin." (PMID 38525337, 2024). "The rationale for improvements in conditions such as diabetic neuropathy, retinopathy, nephropathy, etc., may be related to improvements in glucose utilization and signaling associated with the physiologic administration of insulin." (PMID 37446104, 2023). "Retinopathy and nephropathy were more frequent in severe insulin-deficient and neuropathy in MOD." (PMID 38028250, 2023). "Furthermore, dietary fiber can reduce the progression of kidney disease in susceptible and high-risk individuals by improving glycemic control, increasing insulin sensitivity, decreasing oxidative stress, and reducing the GI of the diet." (PMID 36532536, 2022). "The time‐dependent Cox regression analysis identified neuropathy, peripheral arterial disease, nephropathy and male gender to be associated with an increased risk of subsequent foot complications, while higher age at diagnosis and use of insulin was associated with decreased risk." (PMID 34505418, 2021). "Notably, the development of kidney disease itself has been linked to the loss of renal insulin sensitivity and to mitochondrial changes in multiple renal cell types." (PMID 31195596, 2019). "Although the total direct costs of liraglutide added to basal insulin were higher than those for lixisenatide added to basal insulin, direct costs associated with complications, particularly for nephropathy, and indirect costs (i.e. production losses) were lower." (PMID 29408938, 2018). "Of these patients, two were taking insulin and oral hypoglycaemic medication (both with unknown cause of renal disease), and three were taking oral hypoglycaemic medication only (two patients with IgA nephropathy, and one with renovascular disease)." (PMID 30303980, 2018). "Using multiple linear regression with log transformation, the total cost of DM was significantly associated with DM treatments (taking insulin only or both oral medications and insulin) and DM-related complications (cerebrovascular, cardiovascular, and peripheral vascular diseases and nephropathy)." (PMID 25816299, 2015). "The hyperglycemic state developed from either a deficiency in insulin secretion or an impaired cellular resistance to the action of insulin is associated with a number of complications, leading to retinopathy, nephropathy, peripheral neuropathy, angiopathy and impaired wound healing." (PMID 26740771, 2014). "However, it has been proposed that the chronic elevation of blood leptin may be associated with altered signalling of both insulin and leptin, dysregulation of lipid metabolism, blood pressure, and kidney diseases." (PMID 36064746, 2022). "Despite continuing innovation in blood glucose monitoring for insulin replacement therapy for T1D, suboptimal regulation of blood glucose levels persists as the cause of the chronic debilitating complications (e.g. retinopathies, nephropathies, heart disease) faced by T1D patients." (PMID 25197614, 2013). "MASLD links to kidney disease, indicating shared metabolic risks and chronic kidney disease connections via systemic inflammation, insulin resistance, and RAAS activation." (PMID 41056021, 2026). "Decreased C-peptide was associated with worse blood sugar management, increased instances of retinopathy, nephropathy, and neuropathy, as well as greater need for insulin treatment." (PMID 41185830, 2025). "Overall, Pakistanis were more likely to be prescribed insulin and develop nephropathy than Bangladeshis, despite being prescribed anti-diabetic medications from more classes." (PMID 39592779, 2025).
Nephropathy (continued). "The proportions of patients who received sulfonylurea and insulin therapy and developed neuropathy, retinopathy, and nephropathy were high in the High GRI group." (PMID 40049179, 2025). "Key areas of interest include metabolic dysfunction, insulin, IR, inflammation, and oxidative stress, which drive the progression of both liver and kidney diseases." (PMID 40507673, 2025). "Renal disorders result from metabolic disorders, specifically insulin resistance, dysfunctional fats, and carbohydrate metabolism." (PMID 40703753, 2025). "This multicenter, randomized, controlled clinical trial involving 1441 subjects revealed reduced risks of diabetic retinopathy, nephropathy, neuropathy, and macrovascular disease in the cohort receiving intensive insulin treatment compared to standard therapy." (PMID 38397323, 2024). "As reported in this study, the S1 compound assists the beta cell’s condition with maximum insulin secretion and a lower rate of diabetic-related diseases (nephropathy, liver toxicity)." (PMID 38565861, 2024). "Elevated interleukin-6 (IL-6) levels further intensify inflammation and oxidative stress, disrupting insulin signaling and worsening complications such as nephropathy, retinopathy, and neuropathy." (PMID 39857603, 2024). "The HbA1c level, insulin dose, and diabetic chronic complications, including neuropathy, retinopathy, and nephropathy, were evaluated after 5 years." (PMID 38786050, 2024). "Chronic exposure to fluoride affects collagen biosynthesis, insulin resistance, diabetesmellitus and kidney damage." (PMID 39917236, 2024). "C-peptide is an indicator of insulin secretion by functioning pancreatic beta cells, and high levels of C-peptide indicate possible resistance to insulin, beta cell neoplasm or kidney disease." (PMID 38314402, 2024). "Significant harm arises from the use of insulin/dextrose for the management of hyperkalaemia in patients with renal disease." (PMID 38871123, 2024). "These are reported to decrease fasting and postprandial blood glucose, reduce cholesterol and oxidative stress, and improve renal disorders, fat metabolism, cell viability, and insulin secretion." (PMID 39519546, 2024). "Hypokalemia can be due to several causes; these include medications such as diuretics and laxatives, diarrhea, renal diseases like types I and II renal tubular acidosis, inadequate nutrition, and insulin overdose." (PMID 39759753, 2024). "It leads to extensive complications such as cardiovascular disease, nephropathy, retinopathy, and peripheral and central nervous system through an inability to produce or respond to insulin." (PMID 37134105, 2023). "The present investigation found that in the diabetic patients with the nephropathy group, the hsa-miR-221 concentrations were positively correlated with BMI, fasting insulin, fasting glucose, HOMA IR, and urinary ACR." (PMID 37831346, 2023). "Example: 65 years old; male; history of heart failure, cerebrovascular disease, moderate or severe kidney disease, moderate or severe liver disease, and cancer; use of insulin; HbA1c level = 12.00%, HDL‐C level = 1.00 mmol/L." (PMID 36526273, 2023). "The final prediction model included age, sex, heart failure, cerebrovascular disease, moderate or severe kidney disease, moderate or severe liver disease, cancer, insulin use, glycosylated hemoglobin, and high‐density lipoprotein cholesterol." (PMID 36526273, 2023). "The disruption of insulin signaling can occur due to kidney disease, particularly in its advanced stages." (PMID 37868469, 2023). "Inflammation is an important contributor to several complications in kidney disease, for instance, increased protein degradation rate of skeletal muscle, lesser creation of muscle protein, and insulin resistance." (PMID 36995004, 2023). "Simultaneous pancreas kidney (SPK) transplantation is an invaluable procedure to enhance the quality of life of insulin-dependent patients with advanced renal disease." (PMID 37885028, 2023).
Nephropathy (continued). "Current studies found that ACE inhibitors, angiotensin receptor blockers, anti-hypertensive agents, diuretics, insulin, and statins are potential risk factors for AKI or other kidney diseases." (PMID 37237361, 2023). "Severe nephropathy can reduce insulin excretion and paradoxically lead to lower HbA1c levels as well." (PMID 35519534, 2022). "Another study, also conducted on the HK-2 cells, but treated with palmitate instead of glucose, also focused on HPE effect on nephropathy resulting from insulin action alterations." (PMID 35885378, 2022). "There is a consensus that metabolic acidosis leads to insulin resistance, breakdown in skeletal muscle mass, and cardiovascular complications in addition to progression of kidney disease." (PMID 36572862, 2022). "It protects islet β-cell function and can promote insulin secretion, thereby reducing blood glucose and delaying the process of renal disease." (PMID 35692408, 2022). "Later, 20 subjects were excluded due to the following reasons: withdrawals, using supplements, the increased need for medications, kidney disease, and insulin therapy." (PMID 36514747, 2022). "Chronic hyperglycemia that results from insufficient insulin secretion and/or the inability to use insulin effectively can lead to serious life-threatening conditions, including cardiovascular problems, retinopathy, nephropathy, and neuropathy." (PMID 33564524, 2021). "Our study revealed statistically significant associations of DF with neuropathy, peripheral arterial disease, nephropathy and use of insulin or insulin analogues." (PMID 34505418, 2021). "Average chronic glycemic control was good (mean HbA1c = 53.3 ± 11.9 mmol/mol, with one in every six patients already being treated with insulin and one third who had already had retinopathy, neuropathy or nephropathy." (PMID 34315938, 2021). "A mutation in the HNF1B gene results in MODY5, which is characterized by reduced insulin secretion and usually a renal disease." (PMID 33477506, 2021). "Although not reaching significance, patients with poor glycaemic control had a higher likelihood for AD (OR = 1.7), as did patients on insulin injection (OR=1.4) and patients with renal disease (OR=1.4)." (PMID 34956794, 2021). "Group 2 compared with Group 1 had significantly (p < 0.05) higher mean concentrations of glycated hemoglobin (HbA1c), glucose, triglycerides, and insulin, along with higher rates of metformin use, smoking, retinopathy, and nephropathy." (PMID 32267365, 2020). "The mean concentrations of HbA1c, glucose, triglycerides, and insulin, as well as the rates of metformin use, smoking, retinopathy, and nephropathy, were significantly higher in Group 2 than Group 1 (p < 0.05)." (PMID 32267365, 2020). "Many people struggle with their concerns about insulin and delay insulin therapy until their blood sugar control worsens, at which time it is already sometimes too late to delay or prevent kidney damage." (PMID 32656263, 2020). "The P4P cohort was associated with a reduced mortality rate in most of the stratified analysis, including the elderly (0.69 [0.53–0.90]), insulin users (0.47 [0.35–0.63]), liver disease (0.52 [0.33–0.80]), and renal disease (0.40 [0.20–0.78])." (PMID 32049836, 2020). "Metformin reduces RhoA activity and activates AMPK, while Fasudil, a selective RhoA inhibitor used to treat diabetic nephropathy, improves insulin signaling and nephropathy by correcting glucose and lipid homeostasis in obese Zucker rats." (PMID 30972066, 2019). "During the intervention, 20 subjects were excluded due to the following reasons: using supplements, increased the need for medications, kidney disease, and insulin therapy." (PMID 31827628, 2019).